DPP8 (dipeptidyl peptidase 8)
Description:
Dipeptidyl peptidase that cleaves off N-terminal dipeptides from proteins having a Pro or Ala residue at position 2. Acts as a key inhibitor of caspase-1-dependent monocyte and macrophage pyroptosis in resting cells by preventing activation of NLRP1 and CARD8. Sequesters the cleaved C-terminal part of NLRP1 and CARD8, which respectively constitute the active part of the NLRP1 and CARD8 inflammasomes, in a ternary complex, thereby preventing their oligomerization and activation. The dipeptidyl peptidase activity is required to suppress NLRP1 and CARD8; however, neither NLRP1 nor CARD8 are bona fide substrates of DPP8, suggesting the existence of substrate(s) required for NLRP1 and CARD8 inhibition (By similarity).
Synonyms: DP8; DPRP-1; DPRP1; MSTP097; MSTP135; MSTP141; FLJ14920; FLJ20283; MGC26191; MST097
Tractability: Small molecule: a structure with a bound ligand is known; a high-quality ligand is known; it belongs to a druggable protein family. PROTAC: ubiquitination databases record sites on it; its protein half-life has been measured; a small molecule that binds it is known.
Target class: Enzyme; Serine protease SC clan; Protease; Serine protease S9B subfamily; Serine protease
Chemical probes: cpd 1 (high quality)
Gene: Protein-coding gene on chromosome 15 (65,442,463 to 65,517,724, reverse strand). Ensembl gene ENSG00000074603.
Subcellular location: Cytoplasm
Subcellular location (Human Protein Atlas): Cytosol
Gene Ontology:
Molecular function: dipeptidyl-peptidase activity; protein binding; serine-type peptidase activity
Biological process: negative regulation of programmed cell death; immune response; proteolysis
Cellular component: cytoplasm; cytosol
Genetic constraint (gnomAD): Loss-of-function variants: 16 observed, 66.11 expected, observed/expected ratio (o/e) 0.24, 90% interval 0.16 to 0.37. The upper end of that interval is the gene's LOEUF score, 0.37, which puts it in group 1 of 6, group 1 being the genes least tolerant of losing a copy. Missense variants: 563 observed, 762.72 expected, observed/expected ratio (o/e) 0.74, 90% interval 0.69 to 0.79. Synonymous variants: 268 observed, 262.36 expected, observed/expected ratio (o/e) 1.02, 90% interval 0.92 to 1.13.
Homologues: Orthologues: chimpanzee DPP8 (100% identical), macaque DPP8 (99% identical), dog DPP8 (99% identical), rabbit DPP8 (98% identical), guinea pig DPP8 (98% identical), mouse Dpp8 (96% identical), rat Dpp8 (96% identical), pig DPP8 (91% identical), tropical clawed frog dpp8 (80% identical), Drosophila melanogaster CG3744 (39% identical), Caenorhabditis elegans dpf-3 (30% identical). Paralogues in human: DPP9 (59% identical), DPP4 (21% identical), FAP (20% identical), DPP10 (20% identical), DPP6 (20% identical), APEH (12% identical).
Diseases named in the same sentence as DPP8 in open-access papers:
DPP8 is named in the same sentence as 49 diseases in open-access papers, as found by Europe PMC text mining. Sharing a sentence is not in itself a finding about the gene and the disease. The quoted sentences say what the papers report.
acute myeloid leukemia (15 papers, 2019 to 2025). Acute myeloid leukemia (AML) is a group of neoplasms arising from precursor cells committed to the myeloid cell-line differentiation. "DPP8/9 inhibitors, which induce pyroptosis in acute myeloid leukemia, also activate pyroptosis in other cells, such as B cells and CD34+ cells and augment treatment-associated toxicity." (PMID 36742298, 2023). "DPP8/9 inhibitor induces pyroptosis through CARD8 activation of pro-caspase-1 demonstrated in human acute myeloid leukemia (AML) cell lines and primary AML samples." (PMID 36172198, 2022). "Recently, inhibition of DPP8/9 has garnered attention as a new potential therapeutic strategy for acute myeloid leukemia (AML)." (PMID 31792328, 2019). "Inhibition of DPP8/9 leads to pyroptosis and inhibitors of DPP8/9 could potentially be used to treat acute myeloid leukemia." (PMID 41040322, 2025). "Beyond immune cells, DPP8/9 inhibitors have been shown to induce pyroptosis in acute myeloid leukemia (AML) cell lines and primary AML samples." (PMID 40149884, 2025). "Further studies have shown that DPP8/9 inhibitors-induced pyroptosis in most human AML (acute myeloid leukemia) cell lines and primary AML samples, and these inhibitors also have effects on inhibiting human AML in mouse models." (PMID 34381721, 2021). "Consistently, VBP and the more selective DPP8/DPP9 inhibitor 1G244 were shown to engage the inflammasome adaptor protein CARD8 to induce pyroptosis of a panel of acute myeloid leukemia (AML) cell lines and primary AML samples." (PMID 30718379, 2019). "DPP8 and DPP9 can regulate pyroptosis in human acute myeloid leukemia, while DPP8 and DPP9 mRNAs are overexpressed in ovarian carcinoma." (PMID 34359286, 2021). "DPP8/9 inhibitors selectively induce pyroptotic cell death in human acute myeloid leukemia (AML) cells and inhibit human AML progression in mouse models, highlighting it’s a potential utility for AML treatment." (PMID 33941231, 2021). "As in acute myeloid leukemia (AML) cancer cell lines, we found that CARD8, and not NLRP1, mediates DPP8/9 inhibitor-induced pyroptosis in human T cells." (PMID 32796818, 2020). "Serine dipeptidase DPP8/9 inhibitors, which activate GSDMD-mediated pyroptosis in human myeloid cells, induce pyroptosis in most human acute myeloid leukemia cell lines and primary cells but not cells from other lineages, presenting a novel therapeutic strategy for acute myeloid leukemia." (PMID 36742298, 2023). "Small-molecule inhibitors of the serine dipeptidases DPP8 and DPP9 (DPP8/9) activated CARD8 and caspase-1 to trigger pyroptosis in the majority of human acute myeloid leukemia (AML), indicating the protein CARD8 could be a novel therapeutic target for AML." (PMID 34298833, 2021).
alopecia (4 papers, 2015 to 2024). Hair loss usually from the scalp. "For instance, they showed that different doses of a specific DPP8/9 inhibitor produced alopecia, thrombocytopenia, reticulocytopenia, enlarged spleen, multiorgan histopathological changes and mortality in rats." (PMID 37510747, 2023). "Selective DPP-8 and DPP-9 inhibitors were discovered in a rat toxicity study to be associated with severe toxicities leading to an enlarged spleen, multiorgan histopathological changes, and alopecia." (PMID 39177655, 2024).
breast carcinoma (4 papers, 2021 to 2024). "In breast cancer cell lines, similar DPP8 mRNA and protein levels were detected in MCF-7 (luminal A), MDA.MB-231 (basal-like), and MDA.MB-453 (basal-like) cells." (PMID 37626841, 2023). "In studies of Gynecologic malignancies, DPP8/9 was indicated to be ubiquitous in breast cancer, ovarian cancer, and HeLa cell lines." (PMID 36172198, 2022). "High expression levels of DPP3 and DPP4 were associated with poor survival of breast cancer patients, whereas high expression levels of DPP6, DPP7, DPP8, and DPP9 were associated with good prognoses." (PMID 34359286, 2021). "Results from an Oncomine analysis showed that mRNA expression levels of DPP3 and DPP9 were highly upregulated in breast cancer tissues, whereas DPP4, DPP6, and DPP8 exhibited downregulated levels in breast cancer tissues relative to normal breast tissues." (PMID 34359286, 2021). "Furthermore, combinatory treatment using 4-OHT (SERM) and 1G244 (DPP8/9 inhibitor) reduced proliferation as well as enhanced cell death, demonstrating its potency in ER-positive breast cancer cells." (PMID 37626841, 2023). "Thus, DPP8/9 inhibition led to the accumulation of acidic vesicles in the cytosols of breast cancer cells, and this effect was most prominent in the luminal MCF-7 cells." (PMID 37626841, 2023). "In our study, we investigated the impact of DPP8 and DPP9 on breast cancer cells representing different molecular subtypes." (PMID 37626841, 2023). "In breast cancer, DPP9 expression was elevated, and high DPP8/9 expression correlates with a good prognosis." (PMID 36172198, 2022). "In summary, both DPP8 and DPP9 activities confine macroautophagy in breast cancer cells." (PMID 37626841, 2023). "Data demonstrated that DPP3, DPP7, DPP8, DPP9, and DPP10 mostly had medium protein expression levels, while some clinical tissues showed strong positive expression levels of DPP3, DPP7, and DPP9 in breast cancer specimens." (PMID 34359286, 2021). "Although DPP8 and DPP9 have been shown to influence tumor growth in various entities, like Ewing sarcoma, cervical cancer, or non-small-cell lung cancer, their role in breast cancer is unknown." (PMID 37626841, 2023). "This family comprises seven members, including DPP3, DPP4, DPP6, DPP7, DPP8, DPP9, and DPP10; however, information on the involvement of DPPs in breast cancer is lacking in the literature." (PMID 34359286, 2021). "Our data showed that DPP8 had low expression levels in breast cancer tissues at both the transcription and protein levels whereas DPP9 did not, and both of them were related to good prognoses in breast cancer patients." (PMID 34359286, 2021).
cervical cancer (4 papers, 2021 to 2023). A primary or metastatic malignant neoplasm involving the cervix. "In contrast, DPP9 deficiency in non-small-cell lung cancer cells, as well as DPP8 deficiency in cervical cancer cells, reduced proliferation." (PMID 37626841, 2023). "For example, inhibition of DPP8 expression in cervical cancer cells can inhibit cell proliferation, migration, and invasion by affecting the expression of Bax and BCL2, inhibiting the expression of MMP2 and MMP9." (PMID 36172198, 2022). "We observed that DPP8 and DPP9 LoF variants were more commonly diagnosed with a gynecological cancer, such as UCEC, cervical cancer or ovarian cancer." (PMID 33915844, 2021). "After silencing DPP8 in human cervical cancer cell lines, G1 phase arrest increased Bax expression, decreased BCL2 expression, inhibited cell proliferation, promoted cell apoptosis, and inhibited the expression of MMP2 and MMP9, reducing cell migration and invasion." (PMID 36172198, 2022). "Notably, DPP8 is found to be expressed in cervical cancer tissues and cells of humans." (PMID 38200816, 2023). "Moreover, DPP8 has also been indicated to participate in the pathogenesis of cervical cancer." (PMID 36172198, 2022).
ovarian carcinoma (4 papers, 2013 to 2022). A malignant neoplasm originating from the surface ovarian epithelium. "CXCL10, a substrate of DPP8/9, was also found to play an important role in ovarian carcinoma by immune regulation." (PMID 36172198, 2022). "Elevated DPP8/9 levels were also detected in ovarian carcinoma and their exudates." (PMID 36172198, 2022).
colitis (3 papers, 2022). Inflammation of the colon. "DPP8 and DPP9 are more closely associated with gut inflammation and colitis." (PMID 36468400, 2022).
asthma (2 papers, 2022). "In a rat asthma model induced by sensitization and challenge with ovalbumin, the gene level and enzymatic activity of DPP8/9 in lung tissue of wild-type and DPP4-knockout rats and the enzymatic activity of DPP8/9 in bronchial lavage fluid were upregulated." (PMID 36172198, 2022). "Therefore, DPP8 and DPP9 may be involved in the occurrence and development of chronic inflammatory responses in asthma." (PMID 36172198, 2022).
B-cell chronic lymphocytic leukemia (2 papers, 2013 to 2022). "Abnormal upregulation of DPP8/9 expression can be detected in B-cell chronic lymphocytic leukemia (CLL)." (PMID 36172198, 2022).
diabetes (2 papers, 2015 to 2023). "We used the recombinant DPP8 activity assay to test a panel of potential DPP8 inhibitors: one licensed diabetes drug, vildagliptin, and a series of compounds designed to target human DPP IV/8/9 enzymes." (PMID 25816352, 2015). "Notably, PLCG1 and DPP8 showed excellent discriminative abilities in the prediction of diabetes." (PMID 38034011, 2023).
Ewing Sarcoma Family of Tumor (2 papers, 2022 to 2023). "In Ewing Sarcoma Family of Tumor (ESFT) cells, the knockdown of DPP4, DPP8, or DPP9 leads to NPY-mediated apoptosis." (PMID 37626841, 2023). "Endogenous NPY-driven cell death in Ewing sarcoma family tumors (ESFT) can be blocked by DPPs, including DPP8/9, which also indicates that NPY can serve as an in vivo substrate of DPP8/9." (PMID 36172198, 2022).
leukemia (2 papers, 2016 to 2023). A malignant (clonal) hematologic disorder, involving hematopoietic stem cells and characterized by the presence of primitive or atypical myeloid or lymphoid cells in the bone marrow and the blood. "Recently, it was shown that the vildagliptin-mediated inhibition of DPP-8 and DPP-9 was associated with induction of the leukemia stem cell death." (PMID 27759084, 2016). "Small-molecule inhibitors of the serine dipeptidases DPP8 and DPP9 (DPP8/9) have been shown to induce pyroptosis in human myeloid cells, including cell lines, primary AML samples and mice models of human leukemia." (PMID 37065864, 2023).
meningioma (2 papers, 2013 to 2022). A generally slow growing tumor attached to the dura mater. "It has been implicated that DPP8/9 is expressed in various brain tumors, such as gliomas and meningiomas." (PMID 36172198, 2022). "In contrast, more abundant expression of DPP8/9 was currently detected in meningiomas." (PMID 36172198, 2022).
myeloma (2 papers, 2019 to 2023). "We previously reported that treatment with the DPP8/9 inhibitor 1G244 resulted in apoptotic cell death in myeloma, and our current study further evaluates the mechanism of action of 1G244 in different blood cancer cell lines." (PMID 37048172, 2023). "Taken together, these results indicate that DPP8 is a novel therapeutic target for myeloma treatment." (PMID 31792328, 2019). "We thus concluded that apoptotic cell death signaling was induced in multiple myeloma cells by DPP8/9 inhibition." (PMID 31792328, 2019). "In summary, our present work demonstrated that DPP8 is a novel target for multiple myeloma therapy inducing apoptotic cell death." (PMID 31792328, 2019). "In fact, the expression of DPP8 in CD38+ cells from myeloma patients was higher than that of healthy volunteers." (PMID 31792328, 2019). "Further development of specific inhibitors against DPP8 would provide promising therapeutic effects in human multiple myeloma." (PMID 31792328, 2019). "We have reported that 1G244 triggers caspase-3-activation-mediated apoptosis in multiple myeloma (MM) cell lines and primary MM samples, and that this effect may be dependent on DPP8 inhibition." (PMID 37048172, 2023). "To further address this topic, we employed a specific DPP8/9 inhibitor, 1G24436 to confirm whether DPP8/9 inhibition actually induced cell death in multiple myeloma cells." (PMID 31792328, 2019). "Therefore, our present paper reports for the first time the anti-myeloma activity induced by the DPP8/9 inhibitor." (PMID 31792328, 2019). "Therefore, herein we initially investigated the therapeutic efficacy of DPP4 inhibitors on multiple myeloma cells, work which subsequently led to the interesting findings indicating that DPP8 is a novel therapeutic target for multiple myeloma." (PMID 31792328, 2019). "Although it was demonstrated that Val-boroPro had no activity against any of the non-AML cell lines, it did not necessarily contradict our findings that DPP8/9 inhibition induced cell death in multiple myeloma cells." (PMID 31792328, 2019). "Indeed, DPP8 was expressed at a higher level in CD38+ bone marrow cells of Waldenstrom’s macroglobulinemia and multiple myeloma patients than those of healthy volunteers." (PMID 31792328, 2019).
breast tumor (1 paper, 2023). "In this study, we show that DPP8 and DPP9 play a pivotal role in maintaining autophagic flux and thereby contribute to the better survival of ER-/PR-positive breast tumor cells (luminal A)." (PMID 37626841, 2023).
chronic kidney disease (1 paper, 2022). Impairment of the renal function secondary to chronic kidney damage persisting for three or more months. "Our previous study results revealed that DPP8/9 expression was increased in proximal tubular epithelial cells in patients with chronic kidney disease (CKD)." (PMID 36172198, 2022). "In addition, DPP8/9 inhibitors also have great potential in the treatment of tumors and chronic kidney disease." (PMID 36172198, 2022).
colon adenocarcinoma (1 paper, 2021). "There were 22 DPP8 nonsense mutations in COSMIC, most often in colon adenocarcinoma and one in HCC." (PMID 33915844, 2021).
glioma (1 paper, 2022). A benign or malignant brain and spinal cord tumor that arises from glial cells (astrocytes, oligodendrocytes, ependymal cells). "Non-malignant brain tissue contains DPP4-like enzymatic activity primarily attributable to DPP8/9, it has also been shown that DPP9 is upregulated in glioma." (PMID 36172198, 2022).
hepatocellular carcinoma (1 paper, 2022). A malignant tumor that arises from hepatocytes. "Overexpressed DPP8/9 in patients with hepatocellular carcinoma (HCC) has been observed." (PMID 36172198, 2022).
immunotoxicity (1 paper, 2016). "DPP-8 and DPP-9 inhibition was reported to be associated with multiorgan toxicities and immunotoxicity in rats and dogs and attenuation of human T-cell activation in vitro in some, but not other studies." (PMID 27328054, 2016).
inflammatory bowel disease (1 paper, 2022). A spectrum of small and large bowel inflammatory diseases of unknown etiology. "And in the colorectal tissue of patients with inflammatory bowel disease (IBD), the expression and enzyme activity of DPP8/9 were found to be increased, which indicated that DPP8/9 may be involved in the development of the disease and healing process." (PMID 36172198, 2022).
liver cancer (1 paper, 2021). An epithelial or non-epithelial malignant neoplasm that arises from the liver. "To further investigate DPP4 gene family expression in liver cancer prognosis, we stratified DPP9, DPP8 and DPP4 based on median expression in HCC." (PMID 33915844, 2021).
lung carcinoma (1 paper, 2021). "Supporting this concept, VbP (Talabostat; PT-100; BXCL-701), which exerts potent inhibition of DPP9 and DPP8 and moderate inhibition of DPP4 and FAP, has been shown to lessen tumor burden in lung cancer and sarcoma models." (PMID 33915844, 2021).
melanoma (1 paper, 2025). A malignant, usually aggressive tumor composed of atypical, neoplastic melanocytes. "We were able to correlate DPP8/9 activity and expression in two different melanoma cell lines originating from a primary tumour and a brain metastatic lesion." (PMID 40355159, 2025). "We thus employed DiPAK in a microscopy-based assay to assess DPP8/9 activity in two distinct melanoma cell lines—less aggressive, primary WM1366 and more aggressive, brain metastatic WM3734a cells." (PMID 40355159, 2025). "We identified distinct activity levels among melanoma cell lines and found that LPS-induced primary B-cell activation depends on DPP8/9 as the absence of DPP8/9 activity results in apoptotic but not pyroptotic cell death." (PMID 40355159, 2025).
metastatic tumors (1 paper, 2022). "The expression of DPP8/9 was enhanced in aggressive and metastatic tumors, suggesting that DPP8/9 might be involved in tumor progression." (PMID 36172198, 2022).
myeloid leukemia (1 paper, 2019). A clonal proliferation of myeloid cells and their precursors in the bone marrow, peripheral blood, and spleen. "Consistent with the requirement of a responsive Nlrp1b allele for efficient pyroptosis induction by DPP8/DPP9 inhibitors, 1G244 more potently induced cytotoxicity in the BALB/c-derived myeloid leukemia cell line J774.A1 than in the wild-type B6 primary macrophages." (PMID 30718379, 2019).
renal fibrosis (1 paper, 2021). A final common manifestation of a wide variety of chronic kidney diseases characterized by glomerulosclerosis and tubulointerstitial fibrosis. "However, the recent report that the DPP8/9 inhibitor TC-E5007 can lower collagen deposition in a renal fibrosis model suggests that outcomes of DPP8/9 inhibition might be context dependent." (PMID 34771657, 2021).